FRMD5 (FERM domain containing 5)
Description:
May be involved in regulation of cell migration. May regulate cell-matrix interactions via its interaction with ITGB5 and modifying ITGB5 cytoplasmic tail interactions such as with FERMT2 and TLN1. May regulate ROCK1 kinase activity possibly involved in regulation of actin stress fiber formation.
Synonyms: MGC14161; NEDEMA
Tractability: Antibody: UniProt predicts a signal peptide or a membrane-spanning region. PROTAC: ubiquitination databases record sites on it; its protein half-life has been measured.
Gene: Protein-coding gene on chromosome 15 (43,870,761 to 44,195,271, reverse strand). Ensembl gene ENSG00000171877.
Subcellular location: Membrane; Cell junction, adherens junction
Gene Ontology:
Molecular function: integrin binding; protein binding; protein kinase binding; cytoskeletal protein binding
Biological process: negative regulation of cell motility; positive regulation of cell adhesion; regulation of cell migration; actomyosin structure organization
Cellular component: adherens junction; cytoskeleton; membrane
Genetic constraint (gnomAD): Loss-of-function variants: 16 observed, 49.78 expected, observed/expected ratio (o/e) 0.32, 90% interval 0.22 to 0.49. The upper end of that interval is the gene's LOEUF score, 0.49, which puts it in group 2 of 6, group 1 being the genes least tolerant of losing a copy. Missense variants: 540 observed, 629.21 expected, observed/expected ratio (o/e) 0.86, 90% interval 0.8 to 0.92. Synonymous variants: 244 observed, 232.66 expected, observed/expected ratio (o/e) 1.05, 90% interval 0.94 to 1.17.
Homologues: Orthologues: chimpanzee FRMD5 (100% identical), dog FRMD5 (99% identical), mouse Frmd5 (98% identical), pig FRMD5 (98% identical), rabbit FRMD5 (98% identical), rat Frmd5 (98% identical), macaque FRMD5 (95% identical), guinea pig FRMD5 (92% identical), zebrafish frmd5a (86% identical), tropical clawed frog frmd5 (76% identical), zebrafish frmd5b (74% identical), Caenorhabditis elegans frm-1 (29% identical), and 6 more. Paralogues in human: FRMD3 (53% identical), EPB41L1 (31% identical), EPB41L2 (31% identical), EPB41 (30% identical), EPB41L3 (30% identical), EPB41L5 (28% identical), EPB41L4B (26% identical), EPB41L4A (25% identical), FRMD6 (18% identical), MYLIP (16% identical).
Diseases named in the same sentence as FRMD5 in open-access papers:
FRMD5 is named in the same sentence as 17 diseases in open-access papers, as found by Europe PMC text mining. Sharing a sentence is not in itself a finding about the gene and the disease. The quoted sentences say what the papers report.
colorectal cancer (1 paper, 2021). A primary or metastatic malignant neoplasm that affects the colon or rectum. "Studies performed on the deregulation of the Wnt signaling pathway in colorectal cancer have highlighted FRMD5 as a novel target of the β-catenin/TCF7L2 complex, which plays an important role in tumorigenesis." (PMID 34201607, 2021). "Partly, the effect of FRMD5 on the metastatic potential of PTC cells stays in accordance with previously published studies on glioblastoma, lung, and colorectal cancer (mentioned in the Introduction), suggesting its pro-migratory potential." (PMID 34201607, 2021).
ependymoma (1 paper, 2023). A WHO grade II, slow growing tumor of children and young adults, usually located intraventricularly. "However, normal glial cells and glia-like tumor cells have their specific lineage-associated genes, such as FABP7 and MSX1 in normal ASCs, OLIG2 and OPCML in normal OPCs and OLs, FRMD5 in ASC-like ependymomas and GLUL in OPC/OL-like ependymomas." (PMID 37095395, 2023).
lung carcinoma (1 paper, 2021). "FRMD5 is also a protein coding gene which is involved in cell migration and has been linked to lung cancer progression." (PMID 33946483, 2021).
Nystagmus (1 paper, 2024). Rhythmic, involuntary oscillations of one or both eyes related to abnormality in fixation, conjugate gaze, or vestibular mechanisms. "The genetic and phenotypic overlap strongly supports that FRMD5 is the causative gene linked to nystagmus in our patients." (PMID 39583022, 2024). "This study describes a large family from southern Sweden, with a previously undefined autosomal dominant form of early onset episodic nystagmus that segregates with a missense variant in FRMD5." (PMID 39583022, 2024). "Despite differences regarding age of onset, mode of inheritance and different beating direction of the nystagmus seen in our patients and patients with FIN, it is notable that mutations in a gene that is similar to FRMD5 are associated with a phenotype that resembles the phenotype in our patients." (PMID 39583022, 2024).
thyroid cancer (1 paper, 2021). "Here, we performed an analysis on the role of FRMD5 in thyroid cancer, as we found significant discrepancies in FRMD5 expression between BRAF- and RET-mutated PTCs, as well other types of TCs (TCGA and microarray data analysis of clinical specimens)." (PMID 34201607, 2021). "Based on analyses of FRMD5 expression in human thyroid cancer tissue, it was concluded that the high expression of the FRMD5 gene may be associated with the presence of the BRAF V600E genetic aberration." (PMID 34201607, 2021). "Based on analyses of FRMD5 expression in human thyroid cancer tissue, it was concluded that high expression of the FRMD5 gene may be associated with the presence of the BRAF V600E genetic aberration." (PMID 34201607, 2021). "Here, we performed an analysis on the role of FRMD5 in thyroid cancer specimens and cell lines, as we found significant discrepancies in FRMD5 expression between BRAF- and RET-mutated PTCs, as well other types of TCs (TCGA and microarray data analysis of clinical specimens)." (PMID 34201607, 2021).
thyroid tumor (1 paper, 2021). A benign or malignant neoplasm affecting the thyroid gland. "The results suggest that the FRMD5 protein can play an important role in controlling the metastatic potential and multidrug resistance of thyroid tumor cells." (PMID 34201607, 2021).
cancer (4 papers, 2021 to 2025). A tumor composed of atypical neoplastic, often pleomorphic cells that invade other tissues. "Our findings indicate that the biological properties of FRMD5 are strongly dependent on the mutational status of cancer cells." (PMID 34201607, 2021). "The data suggest that the mutational status of the cancer-driver BRAF gene might be crucial for the regulation of the expression of FRMD5 and its activity in PTC cells." (PMID 34201607, 2021). "Of these genes, we found Sh3kbp1, Frmd5 and Adrm1 (nos 16–18) to be upregulated in both treatments, and they are described in the literature to be involved in cancer prevention." (PMID 40275631, 2025). "According to previous literature reports, high expression of SNAI1 can promote the invasion ability of cancer cells, low expression of FRMD5 can weaken the metastatic ability of cancer cells, and low expression of FSTL3 also has similar functions." (PMID 36925652, 2023). "In HCC with HBx truncated at C-terminus (HBxΔC), Cav-1 was upregulated at the transcriptional level, thereby promoting cancer aggressiveness via the LRP6/β-catenin/FRMD5 signaling axis." (PMID 34168559, 2021). "Since depletion of FRMD5 displays mixed oncogenic activity depending on the cancer cell mutational status, the expressional profile of P-gp-, BCRP-, MRP1- and MRP6-encoding genes was evaluated in FRMD5-knocked-down TPC1 and BCPAP cells using RT-qPCR." (PMID 34201607, 2021). "In conclusion, we have provided a novel insight into the role of FRMD5 in cancer cell biology." (PMID 34201607, 2021). "In the subsequent cell activity and apoptosis experiments, we found that the low expression of SNAI1, CDR2L, FRMD5, and FSTL3 could reduce the activity of cancer cells and increase the apoptosis rate of cancer cells." (PMID 36925652, 2023). "Nevertheless, our findings also imply its antimetastatic character in BRAF-mutated cells, indicating that the expressional status and functions of FRMD5 may not be dependent on the type of cancer tissue but rather on genetic alternations in cancer cells." (PMID 34201607, 2021).
tumor (3 papers, 2018 to 2023). "An observed predominant activation of FRMD5 in BRAF-mutated specimens was tested in BRAF V600E tumor samples using Western blot analysis." (PMID 34201607, 2021). "Although several members of this family have already been linked with tumor progression, the role of FRMD5 in cellular biology and tumorigenesis remains unclear." (PMID 34201607, 2021). "The HRI signature consists of 11 HRDEGs, and we focused on the 5 key genes (RGS16, SNAI1, CDR2L, FRMD5, and FSTL3), which exhibited elevated expression levels in tumor tissues and are prognostic risk factors for CC." (PMID 36925652, 2023). "As a particular focus was given to the expressional status of FRMD5 in BRAF-mutated PTCs, an analysis of FRMD5 activation status was performed on the BRAF-like molecular subtype of PTC and compared with other TC types and non-tumor (control) specimens." (PMID 34201607, 2021). "The results demonstrated that RGS16, SNAI1, CDR2L, FRMD5, and FSTL3 consistently exhibited significantly higher relative mRNA expression levels in CC tumor samples than in paired adjacent normal tissues." (PMID 36925652, 2023). "The mRNA expression levels of RGS16, SNAI1, CDR2L, FRMD5, and FSTL3 were higher in tumor samples than that in adjacent normal tissues in TCGA-COAD cohort, suggesting that these five key genes participate in the progression of CC." (PMID 36925652, 2023). "The nature of imbalance in FRMD5 intracellular yield and expression observed in cells harboring BRAF-wt and BRAF V600E is not clear and might result from overall unequal gene expressional profiles, which determines phenotypic features and unique tumor biology cells harboring these mutations." (PMID 34201607, 2021). "Low expression of SNAI1, CDR2L, FRMD5, and FSTL3 could induce cell viability and promote tumor cell apoptosis." (PMID 36925652, 2023). "The average expression of FRMD5 in tumor samples was ~3-fold higher than in non-tumor controls." (PMID 34201607, 2021). "FRMD5, similar to FRMD3, has been reported as a FERM and FA domain-containing novel tumor suppressive molecule, which may maintain cell-cell contact and regulate tumor progression." (PMID 29870543, 2018).
FRMD5 also shares sentences with these, for which no sentence is quoted: congenital stationary night blindness (1 paper); glioblastoma (1); Infertility (1); leiomyoma (1); neurodevelopmental disorder (1); Obesity (1); Opsoclonus (1); Papillary Thyroid Carcinoma (1); type 2 diabetes mellitus (1).